TNF (tumor necrosis factor)
Diseases named in the same sentence as TNF in open-access papers (continued):
Sharing a sentence is not in itself a finding about the gene and the disease.
COVID-19 (continued). "They identified drugs targeting IL-1β, IL6, IL-6Rα, and TNF-α, as well as corticosteroids, through interactome mapping between COVID-19-related proteins and their known drug targets according to current therapeutic approaches." (PMID 37631998, 2023). "This complies with the existing literature, where higher TNF-α values have also been demonstrated in individuals with post COVID-19 symptomatology." (PMID 37894054, 2023). "Finally, we investigated the expression levels of CD147 mRNA between patients with COVID-19 and controls, as well as whether the three genotypes of rs8259T>A were associated with abnormal levels of CD147, miR-492, and TNF mRNA expression in patients with COVID-19." (PMID 37630479, 2023). "Our data corroborate the previously reported increase in antiviral/proinflammatory cytokines IFN-α, TNF, IFN-γ IL-1, IL-6, IL-8, IL-17, and IL-33 in COVID-19, confirming the association between high IL-6 levels and disease severity." (PMID 37174682, 2023). "For example, C-reactive protein (CRP), interleukin 6 (IL-6), and tumor necrosis factor alpha (TNFα) were significantly higher in patients with persistent symptoms after COVID-19 compared to patients that fully recovered." (PMID 37789266, 2023). "Repurposing anti-TNF as a therapy for the treatment of COVID-19 has been suggested in a number of recent publications." (PMID 36674700, 2023). "Anti-TNF-α had an immediate beneficial effect on the virus-induced cytokine storm in both children and adults with active Crohn's disease and COVID-19." (PMID 36698148, 2023). "Altogether, those reports support the benefits of TNF-α inhibitors in slowing the progression of COVID-19 and the potential of anti-TNF-α therapy in preventing adverse outcomes among COVID-19 patients." (PMID 37047115, 2023). "The serum IL-6, IL-8, TNF-α, and IL-1β levels were reported to be elevated in hospitalized patients with COVID-19." (PMID 36864432, 2023). "According to the literature data, cytokines IL-1, IL-6, IL-8 and TNF-α participate in immune response in patients with COVID-19." (PMID 37895467, 2023). "COVID-19 Patients with high IL-10, IL-23, and TNF-α on admission are more likely to experience a severe form of the disease; therefore, those patients should be cautionary monitored and treated." (PMID 37283736, 2023). "Recent studies revealed that elevated levels of TNF-α and IL-6 were observed in COVID-19 patients with injury." (PMID 36671484, 2023). "In this line, TNF-α blocking can provide a favorable therapeutic intervention for the treatment of COVID-19." (PMID 37109231, 2023). "KEGG analysis of MPXV infection showed involvement of MPXV in COVID-19, cytokine-cytokine receptor interaction, and TNF signaling pathway." (PMID 37006463, 2023). "Regarding the inflammatory response, TNF-α, IL-1β, IL-6, GM-CSF, IL-8, IL-4, and IL-10 are involved in BA to alleviate COVID-19, ALI, PF, COPD, PAH, and asthma." (PMID 37007037, 2023). "COVID-19, in addition to upregulating pro-inflammatory cytokines such as interleukin 1 (IL-1), IL-6, and tumor necrosis factor (TNF-α) also leads to higher concentrations of the anti-inflammatory cytokine IL-10." (PMID 36678211, 2023). "Early into the pandemic, those diagnosed with COVID-19 were found to display significantly elevated proinflammatory responses, including increased levels of IL-6, TNF, IL-2, IL-1β, IP-10, IFNγ, MCP1 and MIP1α." (PMID 37091818, 2023). "Inflammation caused by PM, and COVID-19 pathogenesis share multiple signaling pathways (TLR, NLR, Nrf2, NF-κB, TNF, IL-1, IL-17, and JAK-STAT), which further reinforces this connection." (PMID 36680215, 2023). "Pathway and process enrichment analyses of the exclusively expressed proteins showed their high association with COVID-19 and SARS-CoV-2 signaling, as well as with immune response features such as tumor necrosis factor production and complement activation." (PMID 37681923, 2023).
COVID-19 (continued). "COVID-19 induces an increase in cytokine levels, including tumor necrosis factor, interleukin-1, interleukin-6, procalcitonin, and interferon." (PMID 36798637, 2023). "Here, we observed that TNF-α is strongly produced by NK cells of COVID-19 patients with severe COVID-19 and more significantly in CD56bright NK cells from patients with a fatal outcome." (PMID 37342247, 2023). "The reduction in TNF-α levels in CD8+ T cells following viral stimuli in COVID-19-vaccinated patients with active tuberculosis suggests a potential negative immunomodulatory effect of the combined immune response of vaccination and against Mtb." (PMID 38004820, 2023). "Our study data suggest that the function of monkeypox is similar to that COVID-19 in terms of cytokine signaling in the immune system and TNF signaling." (PMID 37006463, 2023). "In fact, transcript levels for the pro-inflammatory cytokines TNF-α, IL-6, and MMP8 in biopsies from COVID-19-associated AKI patients were comparable to those found in normal controls." (PMID 36979824, 2023). "Increased cytokine levels in COVID-19 including IL-1β, IL-6, interferon-inducible protein 10 (IP-10), TNF-alpha, IFN-γ, macrophage inflammatory protein (MIP) 1α and 1β, and vascular endothelial growth factor (VEGF) were observed." (PMID 37753372, 2023). "The inhibitory effect of VPA on inflammatory cytokines, such as TNF-α and IL-6, has been considered to prevent the generation of cytokine storms by COVID-19." (PMID 37762894, 2023). "Anti-TNF-α drugs, such as adalimumab or infliximab, can reduce the death rate in COVID-19 sufferers, according to preliminary clinical data." (PMID 37124230, 2023). "Herein, we demonstrated that COVID-19 patient–derived EVs or viral spike protein triggered-pEVs that carried miR-21/let-7b induced IL-1β/TNF-α/IL-8 upregulation in neutrophils by interacting with TLR7/8 to activate NF-κB." (PMID 37904132, 2023). "As expected, the plasma concentrations of proinflammatory cytokines IFN-γ, IL-6, IL-8, MCP-1, macrophage inflammatory protein (MIP)-1α, MIP-1β and TNF-α were elevated in COVID-19 subjects." (PMID 37205106, 2023). "Our study found that COVID-19 patients have upregulated pathways in apoptotic signaling pathways and response to virus/viral process, including genes TNF, TNFAIP3, TNFSF10, TNFRSF1B, TNFRSF1." (PMID 37949875, 2023). "Referring to blood cytokines, in COVID-19 patients there is a significant reduction in TNF (p < 0.0001) and IL-1β levels (p < 0.0001)." (PMID 36861136, 2023). "In COVID-19-derived monocytes, TNFα, IL1β, IL6, IL10, CXCL8/IL8, and COX2 were also significantly increased, depending on disease severity." (PMID 37310504, 2023). "Measurement of IL-10, IL-23, and TNF-α are the best markers for predicting in-hospital mortality in COVID-19; they have potential prognostic values in SARS-CoV-2 infection." (PMID 37283736, 2023). "The COVID-19 mRNA vaccines occasionally have double-stranded mRNA contaminants which are potent inducers of TNF-α and IFN-y." (PMID 36851240, 2023). "Produced by innate immune cells, increased TNF-α is a major regulator of the early pro-inflammatory response to viral infection in patients with COVID-19." (PMID 37896963, 2023). "Of note, the findings bolster the suggestion of adopting TNF-α inhibitors in reducing hospitalization and death rate among COVID-19 patients." (PMID 37047115, 2023). "The main cytokines produced due to the immune response in severe COVID-19 are interleukin (IL)-1, IL-2, IL-6, and tumor necrosis factor (TNF)." (PMID 37927596, 2023). "For example, the NCT04792021 clinical trial evaluated the pharmacological efficacy of NAC (600 mg twice daily) on oxidative stress, TNF-α, and complications in patients with COVID-19." (PMID 37534078, 2023). "Overall, higher serum IL-1 β, IL-6, and TNF-α levels were reported in COVID-19 compared to periodontitis." (PMID 37106750, 2023).
COVID-19 (continued). "The worsening clinical state in COVID-19 is related to the elevation of pro-inflammatory cytokines, such as TNF-α and IL-6, in a condition known as cytokine storm." (PMID 37686837, 2023). "Research shows that LMWHs can interact with chemokines and cytokines, which are produced in the “cytokine storm” of COVID-19, and inhibit the release of different cytokines (IL-4, IL-5, IL-13, and TNF-α)." (PMID 37765064, 2023). "Convalescent COVID-19 children had elevated levels of IFNγ, IL-2, TNFα, IL-1α, IL-1β, IFNα, IFNβ, IL-6, IL-12, IL-17A, IL-10 and G-CSF in comparison to control children." (PMID 37013538, 2023). "Few studies in the Eastern Mediterranean Region reported higher serum levels of IL-1β, IL-6, IL-8, and TNF in severe COVID-19 patients compared to mild cases." (PMID 37228441, 2023). "TNF-α levels were significantly higher on days 0, 14, and 28 in the COVID-19 group, with a slight reduction on day 7 compared to the control group." (PMID 37034572, 2023). "Several preclinical studies reported that the type I IFN response co-occurs with proinflammatory cytokine responses such as TNF-α and IL-1β, which is a major feature of severe COVID-19." (PMID 36989209, 2023). "On the contrary, OAS1 risk alleles for AD and severe COVID-19 are all linked with decreased OAS1 expression, which exaggerates the production of TNF-α with IFN-γ stimulation." (PMID 36717892, 2023). "In this regard, it has been suggested that activation of PPARγ during COVID-19 can reduce the circulating levels of TNF-α, IL-1, and IL-6 in the innate immune cells such as macrophages and monocytes through interaction with NF-κB." (PMID 36875108, 2023). "Patients with serious COVID-19 illness had high IL-6, IL-8, and TNF-α levels, along with higher neutrophil and monocyte counts." (PMID 37754237, 2023). "Mapping relation examination between COVID-19 and Ephedra-Glycyrrhiza exhibited that the key markers were tumor necrosis factor-α (TNF-α), interleukin-2 (IL-2), albumin (ALB), FOS proto-oncogene, and prostaglandin- endoperoxide synthase 2 (PTGS2)." (PMID 37654998, 2023). "Our results have allowed the design of a predictive model for post COVID-19 based on the levels of three cytokines at month 1 (IL-1β, TNF-α, and MIP-1α)." (PMID 37894054, 2023). "COVID-19 mRNA vaccines are known to initiate Th1-biased immune responses associated with increased levels of IL-2, IFN-γ, and TNF, as well as CD4+ and CD8+ T-cells." (PMID 36851087, 2023). "One critical aspect of COVID-19 pathology is the cytokine storm, characterized by an excessive release of proinflammatory cytokines and chemokines like TNF-α, IL-1β, and IL-6." (PMID 37834246, 2023). "As a result, it remains relevant to further define, justify, and delineate the importance of TNF-α in the morbidity and mortality of COVID-19 due to the mixed and inconclusive clinical observations and laboratory analyses." (PMID 37047115, 2023). "Concerning the influence of TNF-α, we found higher values in the group with severe COVID-19 in terms of IgA, IL-10, IL-33, IL-28A and CD40L and lower values of IgM." (PMID 38137381, 2023). "Our data corroborate previous studies that were unable to demonstrate significant differences in terms of the humoral response following COVID-19 vaccination based on the utilized anti-TNF agent (adalimumab, infliximab)." (PMID 37766088, 2023). "Among critically ill patients with COVID-19, serum IL-6 and IL-10 levels are usually higher, while serum GM-CSF, TNF- α, IFN-γ, IL-2 and IL-8 serve as ancillary cytokines with clinical prognostic value in contrast to patients without critical disease." (PMID 37568402, 2023). "In patients with severe and critical course of COVID-19 and with high blood viral excessive type I IFN response causes activation of NFκB-related inflammatory response associated with increased TNF-alpha and IL-6 synthesis." (PMID 37753372, 2023).
COVID-19 (continued). "Our data show that plasma D-dimer concentration in COVID-19 patients was directly related to IL-6 and TNF, and indirectly related to IL-10." (PMID 37408073, 2023). "It has been observed that the level of interleukin (IL)-1, IL-6, interferon (IFN)-γ, granulocyte-macrophage colony-stimulating factor, tumor necrosis factor (TNF) were significantly increased in patients with severe COVID-19." (PMID 37391394, 2023). "This further stimulates several intracellular cytokines, such as NF-κB, mTOR, TNF- α, etc., that contribute to COVID-19’s pathophysiology." (PMID 36817449, 2023). "The observations reflect the feasibility of using TNF-α as a promising molecular predictor of severe COVID-19 in hospitalized patients." (PMID 37047115, 2023). "As the variations in MBL levels were greater in the group of patients with severe acute COVID-19, the levels of the cytokines IL-6 and TNF-α were evaluated in relation to this form of the disease." (PMID 37138871, 2023). "We found significantly higher levels of IL-6 (p = 0.002), IL-8 (p = 0.002), IL-10 (p = 0.006) and TNF-α (p = 0.039) in severe COVID-19." (PMID 37969879, 2023). "This review, therefore, aims to deliberate the immunomodulatory roles of TNF-α in promoting inflammation and its relation with COVID-19 morbidity and mortality." (PMID 37047115, 2023). "COVID-19 patients supplemented with vitamin K2 had reductions in IL-6 and tumor necrosis factor-alpha (TNFα) expression." (PMID 36831641, 2023). "The most enriched pathways for common targets included “Coronavirus disease - COVID-19” and “Influenza A pathway,” and the most enriched pathways in the Environmental Information Processing category were “TNF signaling pathway”." (PMID 38050310, 2023). "High serum levels of IL-1, TNF-a, and MCP-1, in COVID-19 were found as potential risk factors for MASH development." (PMID 37842470, 2023). "Our data agree with another study that verified inflammatory profiles in COVID-19, demonstrating increases in serum levels of IL-1β, IL-6, IL-8, and TNF in patients with COVID-19 compared to healthy donors." (PMID 37018291, 2023). "We showed that the uPA/PAI-1 complex positively correlated with TNFα expression in mononuclear cells from COVID-19 patients." (PMID 38313435, 2023). "Many COVID-19 survivors showed long-term cognitive impairment in executive function and abnormally elevated plasma TNFα levels were negatively correlated with executive function performance in these individuals." (PMID 37873780, 2023). "Resveratrol is also able to decrease the effect of proinflammatory cytokines such as IFN-γ, TNF-α, and IL-1β, which are important factors in the onset of the cytokine storm in COVID-19." (PMID 37299603, 2023). "We found that the brain, lung, and liver tissues from COVID-19 patients contained increased IL-1, IL-8, IL-12, IL-18, and TNF-α." (PMID 36609561, 2023). "In a clinical trial, 18 patients with severe COVID-19 were treated with infliximab-abda, a TNF inhibitor." (PMID 37304177, 2023). "Meanwhile, a recent study indicated that patients with COVID-19 also showed elevated levels of cytokine profiles in their serum, including TNF-α, IL-1, IL-6, and IFN-γ24." (PMID 37363608, 2023). "In mice, during SARS-CoV-2 infection, TNF-α and IFN-γ cause a lethal cytokine shock with tissue damage and exacerbated inflammation in COVID-19." (PMID 37189696, 2023). "Consistent with previous reports, COVID-19 patients displayed higher levels of TNFα, IL-1β, IL-6, IFNα, IFNβ, TGFβ and IL-10 in comparison with HD." (PMID 37063865, 2023). "Multiple immunomodulatory monoclonal antibodies, directed against cytokines such as against tumour necrosis factor alpha (TNF-α), Interleukin (IL)-1, and IL-6, were assessed in COVID-19 patients." (PMID 38203525, 2023). "The cytokine storm is a well-described aspect of a severe SARS-CoV-2 infection and cytokines such as IL-6 and TNF have been shown to correlate to COVID-19 severity." (PMID 37724104, 2023).
COVID-19 (continued). "Our findings are in agreement with previously reported data showing increased levels of inflammatory cytokines, such as IL-1β, TNF and IFNγ, and oxidative stress together with impaired spermatogenesis in men recovering from COVID-19." (PMID 37497433, 2023). "Acute COVID-19 children had significantly elevated levels of cytokines, IFNγ, IL-2, TNFα, IL-1α, IL-1β and IFNα in comparison to convalescent children." (PMID 37013538, 2023). "COVID-19 induces an inflammatory response, resulting in the release of cytokines (cytokine storm) such as tumour necrosis factor-alpha (TNF-α), and interleukins (IL-1, and IL-6)." (PMID 37347738, 2023). "The COVID-19 group had the second poorest placenta damage (placental expression: caspase-3 [10.33±3.64], caspase-1 [5.71±4.29], and TNF-alpha [6.46±4.06])." (PMID 37362630, 2023). "In addition, serum levels of both IL-6 and IL-10 correlated positively with pulmonary lesion volumes on chest CT scans caused by COVID-19, while others argued that the TNF-α/IL-10 ratio could readily estimate progression to acute respiratory failure during COVID-19." (PMID 37568402, 2023). "Though canonical markers of inflammation (IL-6, TNF-α, and CRP) have previously been shown to be associated with higher mortality in supercentenarians and COVID-19 patients, there is an intricate interplay between immune cells and cytokine secretion." (PMID 37928548, 2023). "Elsewhere, lung macrophages induced by MCP-1/CCL2 in patients with COVID-19 and lung involvement have been shown to share a transcriptional phenotype with macrophages stimulated by TNF alpha and IFN gamma." (PMID 37047772, 2023). "First, we measured plasma levels of 8 cytokines (IFN-α, IL-1α, IL-1β, IL-10, IL-6, IL-8, S100A8/A9 (calprotectin), and TNF-α), which were shown to be upregulated in the blood of severe COVID-19 patients." (PMID 38082066, 2023). "Accordingly, anti-cytokine aAbs (e.g., antibodies against IFN-α, IFN-ε, IL-6, IL-22, GM-CSF, and TNF-α) were proposed for COVID-19 and non-COVID-19 treatment, although with different results, since some improved clinical outcomes, while others had no benefit." (PMID 37243300, 2023). "According to severity, it was seen that COVID-19 severe cases have lower production of IL1β at all times analyzed and of TNF at times 4/6 and 45/60 days." (PMID 37515295, 2023). "Increased levels of IL-1β/TNF-α/IL-8 were released from human neutrophils after being stimulated with COVID-19 patient–derived EVs, compared to those in control cells." (PMID 37904132, 2023). "By contrast, adaptative immune response induces a reduction of lymphocyte absolute count in COVID-19 as a consequence of extended TNF-α-induced apoptosis, peripheral consumption, direct ACE-2-cytopathic effect, or through the interaction with CD147." (PMID 37373750, 2023). "Collectively, because of the relationship between COVID-19, long COVID, and TNF-α, it highlights the significance of monitoring the TNF-α level in COVID-19 and PASC patients." (PMID 37047115, 2023). "We found that the EVs of COVID-19 patients contained higher levels of IL-6, TNFα, IL-2, and INFΥ compared to HCs." (PMID 36982991, 2023). "Elevated necrosis factor alpha (TNF-α), interleukin-1 (IL-1), IL-6, levels have been reported in severe COVID-19." (PMID 37712090, 2023). "TNF and IL-8 in COVID-19 patients were additionally increased after one week compared to the levels at admission." (PMID 37174682, 2023). "The cytokine–cytokine receptor interaction (e.g., TNFα/TNFR), JAK-STAT, and other stress response kinases have been targeted with precision drugs, as they were most significantly associated with poor COVID-19 outcomes in transcriptomic and proteomic studies." (PMID 40729168, 2023). "The data obtained in the present study showed that patients with OA and those who recovered from COVID-19 6–9 months before had elevated plasma levels of IL-1β and decreased levels of TNF-α and NF-κB." (PMID 37484856, 2023).